NPAS2 (neuronal PAS domain protein 2)
Diseases named in the same sentence as NPAS2 in open-access papers (continued):
Sharing a sentence is not in itself a finding about the gene and the disease.
prostate carcinoma (continued). "Two other studies were evaluated at gene level and pathway analysis confirmed the correlation between NPAS2 and prostate cancer." (PMID 39011396, 2024). "NPAS2 was identified as part of a gene signature capable of predicting the probability of disease progression in prostate cancer patients." (PMID 37887064, 2023). "NPAS2 is upregulated in prostate cancer and promotes cell survival by promoting glycolysis and inhibiting oxidative phosphorylation in PCa cells." (PMID 36978001, 2023). "In tumor tissue of prostate cancer patients, NPAS2 expression was found up-regulated with respect to matched non-tumorous tissue." (PMID 37887064, 2023). "NPAS2 knockdown in prostate cancer cell lines hindered cell proliferation and increased cell apoptosis in vitro and restrained tumor growth in vivo in xenotransplanted nude mice." (PMID 37887064, 2023). "Our data showed that NPAS2 expression in prostate cancer patient tissue was elevated compared with that in normal prostate tissue." (PMID 36978001, 2023). "To observe the expression of the core rhythm gene NPAS2 in prostate cancer, we firstly analyzed the expression of NPAS2 in 47 PCa tissues and corresponding paraneoplastic tissues by qRT-PCR and IHC." (PMID 36978001, 2023). "Following that, we examined the correlation between HIF-1A and NPAS2 mRNA expression in prostate cancer tissues in the TCGA database." (PMID 36978001, 2023). "NPAS2 is upregulated in prostate cancer and promotes cell survival by promoting glycolysis and inhibiting oxidative phosphorylation through HIF-1A signaling in PCa cells." (PMID 36978001, 2023). "The results showed that NPAS2 expression in prostate cancer patient tissue was elevated compared with that in normal prostate tissue." (PMID 36978001, 2023). "At the molecular level, NPAS2 supported glycolysis and restrained oxidative phosphorylation in prostate cancer cell lines through amplification of hypoxia-inducible factor-1A (HIF-1A)-dependent signaling." (PMID 37887064, 2023). "Epidemiological studies of night shift workers provide strong evidence for the association between prostate cancer and gene variants, including BMAL1, NPAS2, CRY2 and PER2." (PMID 36291899, 2022). "It was reported that aggressive prostate cancer was closely linked with three core circadian clock genes, ARNTL, NPAS2, and RORA." (PMID 34621761, 2021). "Although a limited number of epidemiologic studies have been realized, several circadian genes have been implicated in prostate cancer regulation: ARNTL, CLOCK, CRY1-2, CSNK1e, MTNR1A and MTNR1B, NPAS2, NR1D1, PER1-3, RORA, RORB, and TIMELESS." (PMID 30873119, 2019). "Eight of these, located in four genes, NPAS2 (2 SNPs), CSNK1E (3 SNPs), CRY1 (2 SNPs), and CRY2 (1 SNP), were significantly associated with prostate cancer risk." (PMID 30518396, 2018). "In addition, experimental research also confirmed that NPAS2 expression is increased in tissue from prostate cancer patients when compared to healthy prostate tissue." (PMID 39011396, 2024). "However, the functional roles of NPAS2 in prostate cancer progression remain largely unclear and need further investigation." (PMID 30996687, 2019). "In addition, bioinformatics analysis provided further evidence that rs6542993 is an eQTL that affects the expression of NPAS2, and down-regulation of NPAS2 expression was correlated with a shorter progression-free survival of prostate cancer patients." (PMID 30996687, 2019). "Overall, these findings highlight the importance of NPAS2 in prostate cancer progression." (PMID 30996687, 2019). "A single nucleotide polymorphism of the neuronal PAS domain protein 2 (NPAS2) gene (rs6542993 A>T) was found to be associated with a significantly higher risk of disease progression in both localized (P = 0.001) and advanced (P = 0.039) prostate cancer cases." (PMID 30996687, 2019).
prostate carcinoma (continued). "NPAS2 increases the expression of hypoxia inducible factor-1A (HIF-1a), leading to enhanced glycolytic metabolism in prostate cancer thereby promoting tumor growth." (PMID 39011396, 2024). "The high expression of NPAS2 promotes the release of HIF-1A and key glycolytic genes (HK2, PKM2, GLUT1 and MCT4), enhancing glycolytic metabolite levels, thus inducing the progression of prostate cancer cells." (PMID 36978001, 2023). "The NPAS2 gene expression levels also did not vary significantly when comparing prostate cancers and normal tissues using the MSKCC Prostate Oncogenome Project data." (PMID 30996687, 2019).
Hypertension (12 papers, 2009 to 2023). The presence of chronic increased pressure in the systemic arterial system. "In this regard, genetic variants in circadian genes, NPAS2 included, were found associated with the diurnal phenotype of hypertension, proposing a genetic association with daily blood pressure changes in essential hypertension." (PMID 37887064, 2023). "Human research has recognized polymorphisms and transcription motifs of circadian rhythm genes, such as CRY2, CLOCK, ARNTL, PER2, or NPAS2, which are linked with hypertension, metabolic syndrome, or T2DM." (PMID 32050674, 2020). "Other studies have revealed associations between: polymorphisms in BMAL1 with hypertension and type 2 diabetes, hypertension and NPAS2 (CLOCK gene analogous), and glucose and PER2." (PMID 20712885, 2010). "Npas2 rs11541353 minor allele was protective against hypertension and heterozygosity of Npas2 rs11541353 is protective against Seasonal affective disorder (SAD)." (PMID 19470168, 2009). "Now, we demonstrate herein the associations of Npas2 with hypertension and of Per2 with blood glucose levels." (PMID 19470168, 2009). "Our main results herein are that Npas2 is linked to hypertension and that Per2 is associated with blood glucose levels." (PMID 19470168, 2009). "Combining these results, persons with two major alleles of Npas2 rs11541353 have substantially increased risk not only for SAD but also for hypertension." (PMID 19470168, 2009). "SNP variations in Npas2 have been shown to be linked to hypertension in humans." (PMID 35626652, 2022). "People with the minor allele of SNP rs11541353 of NPAS2 have a low risk of hypertension." (PMID 34460437, 2021). "Npas2 was associated with hypertension and Per2 with blood glucose levels." (PMID 19470168, 2009). "Our findings link circadian gene variants to the risk factors of the metabolic syndrome, since Npas2 was associated with hypertension (P-value corrected for multiple testing = 0.0024) and Per2 was associated with high fasting blood glucose (P-value corrected for multiple testing = 0.049)." (PMID 19470168, 2009). "Npas2 rs11541353 was associated with hypertension in the Finnish population." (PMID 19470168, 2009). "In addition, a missense mutation in the NPAS2 gene was found to be protective against hypertension." (PMID 32722512, 2020). "Our findings now suggest that seasonal weight gain bridges NPAS2 and hypertension to the pathogenesis of the metabolic syndrome." (PMID 20368993, 2010). "Next, the phenotypes in terms of SAD and hypertension in Npas2 rs11541353 homozygous and heterozygous persons need to be analyzed." (PMID 19470168, 2009). "The PubMed and Scopus databases were searched for studies reporting the association between circadian rhythm gene polymorphisms (ARNTL, BMAL1, CLOCK, CRY, PER, NPAS2, REV-ERBα, REV-ERBβ, and RORα) and MetS, and its comorbidities diabetes, obesity, and hypertension." (PMID 35053018, 2021). "In contrast, gene expression profiling of Spontaneously Hypertensive (SHR) rats, a genetic model of hypertension, demonstrated decreased expression of Bmal1 and Npas2, while Per1, Per2, Per3, Cry1, Cry2, Bhlhe41 and Csnk1D were all upregulated compared to naïve WKY controls." (PMID 33127986, 2020). "However, when a person has two Npas2 rs11541353 minor alleles, the results are difficult to interpret, as the homozygosity increases the odds for SAD, but protects against hypertension." (PMID 19470168, 2009).
colorectal cancer (8 papers, 2017 to 2023). A primary or metastatic malignant neoplasm that affects the colon or rectum. "Accordingly, in a study conducted on colorectal cancer patients, lower expression of NPAS2 at mRNA level was found in tumor tissue, correlating with tumor size, tumor–node–metastasis stage and occurrence of distant metastasis." (PMID 37887064, 2023). "Cell propagation and invasion are associated with lower NPAS2 expression that eventually leads to increased wound healing ability in colorectal cancer cells, indicating the pivotal role of NPAS2 in tumor inhibition." (PMID 31151182, 2019). "Silencing NPAS2 expression promoted the proliferation, invasion, and wound healing abilities of colorectal cancer cells, indicating a crucial role of NPAS2 in tumour growth and metastasis." (PMID 30996687, 2019). "Furthermore, in colorectal cancer, suppressing NPAS2 expression boosts cell proliferation and invasion, indicating that NPAS2 plays an important tumor-suppressive role." (PMID 35510040, 2022). "Moreover, researchers have found that a low level of NPAS2 expression exacerbates the associations among tumor size, TNM stage, and tumor distance metastasis in colorectal cancer patients." (PMID 33114496, 2020). "In related work, NPAS2 was found to function as a potential tumor suppressor gene, and it might serve as a prognostic biological marker for breast cancer and colorectal cancer." (PMID 33114496, 2020). "Indeed, NPAS2 has already been established as a prognostic biological marker in breast cancer as well as in colorectal cancer." (PMID 31151182, 2019). "In addition, experiments performed in vitro using a DLD-1 cell line showed that down-regulation of NPAS2 expression by RNA interference increased cell proliferation and invasion, but not apoptosis, corroborating a potential tumor suppressor role for NPAS2 in colorectal cancer." (PMID 37887064, 2023).
lung carcinoma (7 papers, 2018 to 2024). "High-risk genes in the model, including ANGPTL4, LDHA, and NPAS2, have been reported to promote angiogenesis, glycolysis, drug tolerance, the invasive and migratory potential, and cell cycle and apoptosis in lung cancer patients or cell lines." (PMID 35295857, 2022). "In accordance with our findings, increased expression of NPAS2 has been suggested to indicate poor survival in lung cancer." (PMID 37120564, 2023). "In accordance with the regression coefficient derived from multivariate Cox regression models and expression value of SATB2, HLF, and NPAS2, a TF genomic model was conducted for lung cancer prognosis." (PMID 34925645, 2021). "Collectively, our findings proposed and verified a 3-TF genomic model (SATB2, HLF, and NPAS2) for prediction of lung cancer outcomes." (PMID 34925645, 2021). "Further multivariate Cox regression analyses displayed that SATB2, HLF, and NPAS2 were independently predictive of lung cancer prognosis." (PMID 34925645, 2021). "E.g., the circadian rhythms of ARNTL, RORC and NPAS2 are potentially weak and the circadian rhythm of RORC might also be phase-shifted by several hours in lung cancer." (PMID 39004631, 2024). "For the NPAS2 validation results, we found that high-expressed NPAS2 is positivity enriched in focal adhesion, adherens junction and ECM receptor interaction, which are important signal pathways in lung cancer metastasis." (PMID 37155150, 2023).
Anxiety (6 papers, 2017 to 2025). Intense feelings of nervousness, tension, or panic often arise in response to interpersonal stresses. "For their influence on brain development, genetic variations of circadian genes (e.g., CRY1, CLOCK, and NPAS2) are oftentimes associated psychiatric disorders such as anxiety, mood disorders, and alcohol use." (PMID 36833279, 2023). "Regarding the role played in other diagnosable psychiatric disorders, a series of genetic variants of the NPAS2 gene were statistically associated with anxiety, mood, behavioral, eating, personality, psychotic and autistic spectrum disorders as well as dementia-related disorders." (PMID 37887064, 2023). "As mice with a null mutation in Npas2 have significant phenotypes in anxiety-related behaviors, we sought to determine whether expression of Npas2 changes in response to 3 days of FSS or 6 weeks of UCMS." (PMID 29163035, 2017). "We measured anxiety-like behaviors in mice with a global null mutation in Npas2 (Npas2 null mutant mice) and found that Npas2 null mutant mice exhibit less anxiety-like behavior than their wild-type (WT) littermates (in elevated plus maze, light/dark box and open field assay)." (PMID 29163035, 2017). "Next, to assess if recognition memory differences between fl/fl and cKO mice may be due to an anxiety phenotype following hepatic NPAS2 loss as has been demonstrated previously in a global Npas2-/- model, both groups were subjected to open field arena and light-dark box anxiety trials." (PMID 40069567, 2025). "Npas2 null mutant mice display significantly reduced anxiety phenotypes exemplified by increased time spent in the open arms in elevated plus maze tests and significantly reduced latency to enter the light side of a light-dark box7." (PMID 40069567, 2025). "Npas2 knockdown in the ventral striatum led to a comparable decrease in anxiety-like behaviors, whereas acute or chronic stress increased striatal Npas2 expression." (PMID 37887064, 2023). "Taken together, NAc Npas2 shRNA treated mice tended to show reduced anxiety-like behavior (as compared with scramble shRNA treated mice), suggesting that Npas2 in the NAc contributes to the regulation of anxiety-like behavior." (PMID 29163035, 2017). "To draw comparison, we observe that Npas2 mutants and NAc Npas2 KD results in reduced anxiety-like behavior." (PMID 29163035, 2017). "Previous reports, in conjunction with the studies presented here, support a model whereby VTA Clock is important for negatively regulating reward and anxiety and NAc Npas2 is important for positively regulating reward and anxiety." (PMID 29163035, 2017). "Together, these findings suggest that knocking down NAc expression of Npas2 recapitulates some of the reduced anxiety-like behaviors seen in the Npas2 mutant mice." (PMID 29163035, 2017). "In the current studies, we sought to determine the influence of Npas2 on anxiety-related behavior, the effects of anxiogenic stimuli on Npas2 expression, and expand our knowledge of the transcriptional targets of NPAS2." (PMID 29163035, 2017). "We propose that expression of the circadian transcription factor, Npas2, is important for stress responses and anxiety-related behaviors and regulates GABAergic inhibitory neurotransmission in MSNs of the NAc." (PMID 29163035, 2017). "In order to determine if functional NPAS2 is important for anxiety-like behavior, we assayed Npas2 null mutant and WT mice littermates in a battery of anxiety-related behavioral tests." (PMID 29163035, 2017). "Because Per1 and Per2 negatively regulate NPAS2/BMAL1 transcription, this further supports a role for NPAS2 in the regulation of anxiety-like behaviors." (PMID 29163035, 2017). "Selective knockdown of Npas2 in the NAc results in reduced anxiety-like behavior, similar to Npas2 mutant mice." (PMID 29163035, 2017).
Anxiety (continued). "Taken together, these findings support the existence of a homeostatic mechanism by which stress and anxiety increase NPAS2-dependent transcription of specific GABAergic subunits that selectively alter phasic, synaptic inhibitory neurotransmission." (PMID 29163035, 2017). "Here we link Npas2 to responses to stressful and anxiogenic stimuli, expression of anxiety-like behavior, regulation of specific GABAa subunit expression, and inhibitory neurotransmission in the nucleus accumbens." (PMID 29163035, 2017). "Our present research focuses on determining whether the circadian gene, Npas2, is important for the expression of anxiety-like behaviors." (PMID 29163035, 2017). "Npas2 mutant mice exhibited decreased anxiety-like behaviors as compared with WT mice." (PMID 29163035, 2017). "Compared with WT mice, Npas2 null mutant mice exhibited reduced anxiety-like behavior as seen by the increased percent time spent in the open arms of the elevated plus maze (Mann-Whitney test, Npas2 null mutant median = 7.75, n = 24, WT mean = 2.09, n = 16, U = 115, p = 0.032)." (PMID 29163035, 2017). "In addition to (or possibly as a result of its role in circadian regulation) there is evidence that Npas2 may also have other central nervous system behavioural functions in anxiety, cognition, and memory." (PMID 40069567, 2025). "In mice, knock down of the Neuronal PAS Domain Protein 2 (NPAS2), period (PER), or cryptochrome (CRY) genes results in altered anxiety levels." (PMID 35365695, 2022). "To determine if Npas2 is important for the expression of anxiety-like behaviors, we subjected mice lacking functional Npas2 to a battery of behavioral tests." (PMID 29163035, 2017).
depression (6 papers, 2010 to 2025). "NPAS2 has been associated with depression in previous reports, but the nominally significant SNPs in our report were not noted as suggestive in the previous work." (PMID 23521777, 2013). "On the other hand, CRY1 and NPAS2 appeared to be associated to major depression disorder." (PMID 36833279, 2023). "NPAS2 rs12712083, as well as a non-synonymous coding SNP located on exon 5 rs2063690 of TIPIN (Ala111Gly), were associated with depression and fatigue (P = 0.045, OR = 0.72 and P = 0.037, OR = 1.71, respectively)." (PMID 20174623, 2010).
glioma (6 papers, 2021 to 2025). A benign or malignant brain and spinal cord tumor that arises from glial cells (astrocytes, oligodendrocytes, ependymal cells). "The researchers studied the impact of CCGs in the development of lower grade glioma and observed that certain genes including RORβ, NPAS2, and CRY1 were linked with elevated or reduced risk of lower grade glioma." (PMID 40495887, 2025). "NPAS2 is a protein coded by the Npas2 gene that heterodimerizes with BMAL1, and its expression in gliomas was associated with patients having poor outcomes and high mortality." (PMID 34361055, 2021). "WGCNA was performed to identify the genes that were coexpressed with the four key CCGs (ARNTL, NPAS2, CRY2, and DBP) in glioma." (PMID 35832846, 2022). "In summary, we provided a CCGs-based accurate prediction model and showed that ARNTL, NPAS2, CRY2, and DBP had great effects on diagnosis and prognosis of glioma." (PMID 35832846, 2022). "The differential expression of CCGs in glioma grading confirmed that cluster I genes (ARNRL, NPAS2, and TIMELESS) and CRY1, with cluster II genes (CRY2, DBP, NR1D1, NR1D2, PER2, PER3, and RORA) showed significantly opposite expression trends in brain tissues." (PMID 35832846, 2022). "Key CCGs, including ARNTL, NPAS2, CRY2, and DBP, acted as potent diagnosis and prognosis biomarkers of glioma patients and rhythmically regulated cancer-related signaling pathways and coexpressed genes to affect drug sensitivity and possible clinic outcomes." (PMID 35832846, 2022). "Four CCGs (ARNTL, NPAS2, CRY2, and DBP) with rhythmic expression were not only identified as differentially expressed genes but also had significant independent prognostic ability in the overall survival of glioma patients and were highly correlated with glioma prognosis in COX analysis." (PMID 35832846, 2022).